CDC37 (cell division cycle 37, HSP90 cochaperone)
Diseases named in the same sentence as CDC37 in open-access papers (continued):
Sharing a sentence is not in itself a finding about the gene and the disease.
cancer (continued). "Notably, CDC37 overexpression is a hallmark of cancer, and its recruitment to the HSP90 complex promotes oncogenesis, making the disruption of HSP90–CDC37–kinase interactions a potential target for cancer therapies." (PMID 39885126, 2025). "Several studies have shown the importance of targeting CDC37 for cancer therapy." (PMID 39165691, 2024). "New tools may help us understand how Aha1 complexes interact and complement other hetero-oligomeric complexes with Hsp90 co-chaperones including FKBP51 and CDC37 in driving cancers and/or neurodegeneration." (PMID 39776493, 2024). "Our results further confirm that Cdc37 might be a good candidate for broad-spectrum molecular cancer therapy." (PMID 37108830, 2023). "It was also proved that high levels of Cdc37 are observed in some types of cancers." (PMID 37108830, 2023). "CDC37 was correlated with cell proliferation in cancer cells." (PMID 35370699, 2022). "In addition, CDC37 plays a vital role in the epithelial–mesenchymal transition (EMT) of cancer progression." (PMID 35370699, 2022). "Based on the observation that the silencing of Cdc37 sensitizes cancer cells to ATP-pocket binding Hsp90 inhibitors, combinations of the Hsp90/Cdc37 interface and ATP-pocket inhibitors could act synergistically." (PMID 33672199, 2021). "Additionally, several cancer drivers that are Hsp90/Cdc37 client proteins—for example, hormone receptors, HER2, BCR-ABL, B-Raf and Src—were to some extent demonstrated to predict the response to drug treatment." (PMID 33672199, 2021). "However, silencing co-chaperones, such as p23, Aha1, or Cdc37, has resulted in cancer cells becoming dramatically sensitized to HSP90 inhibition." (PMID 34638658, 2021). "Indeed, treatment with anti-CDC37 antibodies impairs cancer cell migration and in vivo administration of an HSP90 blocking antibody, able to disrupt the HSP90-CDC37 complex, inhibits metastasis formation." (PMID 34722515, 2021). "Here, we exploit novel computational and theoretical approaches to design a set of peptides that are able to bind Hsp90 and compete for its interaction with the co-chaperone Cdc37, which is found to be responsible for the promotion of cancer cell proliferation." (PMID 31952296, 2020). "Thus, inhibition of Cdc37 seems to be a promising approach to the treatment of cancer due to its multi-targeting nature." (PMID 32139666, 2020). "Lastly, CDC37 expression is increased in proliferating tissues and is heavily expressed in certain cancers (due to the increased need of over-expressed protein kinases that mediate their growth); whereas most normal tissues do not proliferate or appear to require CDC37." (PMID 25051375, 2014). "Finally we show that the cell impermeable anti-HSP90 mAb 4C5 which has been previously shown to inhibit cancer cell invasion and metastasis has the capacity to impair all the molecular interaction in the Cdc37/HSP90/kinase receptor complex." (PMID 22912728, 2012). "Novel inhibitors that disrupt Cdc37-Hsp90 interactions may thus hold promise as potential therapeutics against a variety of kinase-dependent cancers." (PMID 22624053, 2012). "Together, these results support the targeting of Cdc37 for cancer therapy." (PMID 22912728, 2012). "Like CK2, Cdc37 is over-expressed in cancer cells and a target for cancer therapy." (PMID 22184283, 2011). "Celastrol inhibits NF-κB through targeting IκB kinase and TAK1-induced NF-κB activation, binds to Cdc37 and disrupts the Cdc37–Hsp90N complex which is critical for stabilizing oncogenic kinases in various cancers, and inactivates the p23 protein which is another co-chaperone of HSP90." (PMID 21701438, 2011).
cancer (continued). "In cancer cells, CDC37 could prolong cell survival by activating the CDK4 signaling pathway." (PMID 35370699, 2022). "Therefore, we inferred that celastrol might inhibit cancer cell growth and the cell cycle by downregulating CDC37 expression." (PMID 35370699, 2022). "Furthermore, we have tested the hypothesis that the relationship between MZF1 and SCAND1 regulates CDC37 expression and thereby cancer growth." (PMID 31181782, 2019). "However, less is known regarding the regulation of CDC37 expression in cancer." (PMID 31181782, 2019). "In this pathway, the heat shock protein 90 (HSP90) cooperates with its molecular co-chaperone CDC37 to regulate the folding, maturation, stabilization, and phosphorylation of a wide array of protein kinases, which are important mediators of signal transduction and cell growth in human cancers." (PMID 25051375, 2014). "The targeting of the Hsp90/Cdc37 interaction is a potential alternative to direct Hsp90 inhibition that may offer greater specificity and an improved side effect profile owing to the elevated expression of Cdc37 in cancer." (PMID 24927996, 2014). "Indeed Cdc37 levels are found increased in many clinical cancers." (PMID 22912728, 2012). "Targeting Cdc37/Hsp90 interaction represents a potential alternative to direct Hsp90 inhibition that may offer greater specificity (due to Cdc37 elevated expression in cancer) and an improved side effect profile." (PMID 21342561, 2011). "In response to HSP90 inhibition, the co‐chaperone CDC37 dissociates from RPAP2 and promotes the rapid degradation of RPAP2 via CRL5FBXW7, thereby enhancing the sensitivity of cancer cells to HSP90 inhibitors." (PMID 39932049, 2025). "On the other hand, STK33 has been identified as a survival factor in KRAS-mutant cancers, stabilized by the HSP90/CDC37 complex." (PMID 41009685, 2025). "Interrupting the complex between Cdc37 and HSP90 has surfaced as an alternative focal point for cancer progression." (PMID 38339390, 2024). "In human colon cancer cells, the silencing of Cdc37 destabilizes various kinase clients (AKT, HER2, CDK4, CDK6, and CRAF) and sensitizes cancer cells to HSP90 inhibitors and apoptosis." (PMID 38339390, 2024). "However, Hsp90, together with Cdc37, assists additional proteins that may be relevant in cancer." (PMID 33672199, 2021). "eHSP90, together with its co-chaperone CDC37, also interacts with the family of ERBB receptors, including EGFR or HER2, to promote cancer cell motility and invasion." (PMID 33544155, 2021). "eHSP90-dependent cancer cell migration is impaired by a monoclonal antibody, mAb 4C5, able to disrupt the interaction between CDC37 and HSP90 and CDC37 and ERBB." (PMID 33544155, 2021). "Here, we show that MEK5 or Cdc37 overexpression—two mechanisms that induce nuclear ERK5—results in ERK5 SUMOylation at residues Lys6 and Lys22 in cancer cells." (PMID 32209980, 2020). "Our findings provide insight into how MZF1-driven CDC37 expression promotes cancer progression and how SCAND1 functions as a potential tumor suppressor by repressing CDC37." (PMID 31181782, 2019). "AKT is known as a HSP90 client kinase, and CDC37 can stabilize ERK and AKT kinase activities in numerous cancer cells." (PMID 31572066, 2019). "In this respect, the activity of Hsp90 in cancer cells is highly dependent on other chaperones and co-chaperones like AHA1, p23, HOP (also known as STIP1), CHIP (STUB1), Cdc37, Hsp40 and Hsp70." (PMID 30138434, 2018). "We also show that clinically relevant INK mutants can be selected in cancer cells that inactivate CDK4 and CDK6 through different mechanisms and, as a result, also show differing abilities to displace Cdc37 bound to CDK4 or CDK6." (PMID 29091774, 2017). "It would be interesting to explore in these cancer cells if ERK5 shows constitutive nuclear localization and also collaborates with Cdc37 to promote cell proliferation." (PMID 27713878, 2016).
cancer (continued). "Hop, p23, p50/Cdc37, Aha1, FKBP1, and FKBP2 appear to be intimately involved in the chaperoning of molecules involved in cancer incidence and progression." (PMID 24278769, 2013). "In a noncanonical mechanism, the overexpression of Cdc37 (as it happens in several cancers) also induces Hsp90 dissociation and nuclear translocation of a catalytically inactive—but transcriptionally active—form of ERK5." (PMID 32209980, 2020). "Although it is known that apigenin has a selective inhibitory effect on CK2, it has not known if apigenin kills cancer cells through its capacity to interfere with Cdc37 phosphorylation and to disrupt Hsp90 chaperone function." (PMID 21871133, 2011). "Given CDC37's role as a selectivity module for the HSP90 chaperone, we investigated whether disrupting the ternary complex via two approaches would synergize and promote cancer cell apoptosis." (PMID 41371342, 2025). "Treatment of MDA-MB-468 epichaperome-high cancer cells with these inhibitors resulted in a dose-dependent decrease in epichaperomes, as observed by native PAGE coupled with immunoblotting against epichaperome components such as HSP90α, HSP90β, HSC70, CDC37, HOP, and HSP110." (PMID 39414766, 2024). "Therefore, HSP90 and/or CDC37 are attractive therapeutic targets against various cancers inasmuch as HSP90 and CDC37 are involved in the functionalization of oncogenic proteins in many signaling pathways important for tumor progression, survival, and resistance." (PMID 31533245, 2019). "However, an evaluation of the strategies of killing cancer cells by inhibiting CK2-dependent phosphorylation of Cdc37 has not been reported." (PMID 21871133, 2011). "If so, and given the fact that Cdc37 induces nuclear shuttling of a kinase-inactive form of ERK5, we predict that these cancers will not respond to ERK5 inhibitors." (PMID 27713878, 2016). "As compared with other cancer cell lines and adjacent non-neoplastic tissues, overexpression of CK2 and phosphorylation of CDC37 was demonstrated in GIST cell lines and biopsies, indicating that CK2 could be an important functional regulator in GIST." (PMID 31776458, 2020). "In agreement with their activity as Hsp90/Cdc37 interface inhibitors, both of our novel inhibitors dose-dependently decreased the expression of established Hsp90 clients (C-Raf, Akt, ERK), while not inducing the expression of Hsp90 or Hsp70 in the four cancer cell lines, unlike 17-AAG." (PMID 33672199, 2021).
tumor (39 papers, 2006 to 2025). "Clinically, high tumor CDC37 expression is associated with low infiltration of antigen-specific CTLs and poor ICB efficacy in TNBC patients." (PMID 41215476, 2025). "Formation of active Hsp90/Cdc37 complex is one of the essential steps for facilitation of chaperone client interaction, non-assembly of which can lead to prevention of the chaperone-client association resulting in apoptosis of tumor cells." (PMID 21342561, 2011). "The study conducted here is an attempt to explore the potential of Withania somnifera’s major constituent WA in attenuating the Hsp90/Cdc37 chaperone/co-chaperone interactions for enhanced tumor arresting activity and to elucidate the underlying mode of action using computational approaches." (PMID 21342561, 2011). "CDC37 knockdown in tumor cells or inhibiting CDC37/HSP90 interaction in DCs efficiently promotes antigen translocation and enhances their cross-presentation, which improves ICB therapeutic responses." (PMID 41215476, 2025). "The establishment of tumor in CDC37/c-myc double transgenic males is a result of both CDC37 and c-myc oncogene expression, since expression of either CDC37 or c-myc gene and nontransgenic wild-type males are typically free of proliferative disorders." (PMID 38500604, 2024). "CDC37 plays an important role in proliferation and transformation of tumor cells by maintaining protein kinase activity." (PMID 39165691, 2024). "It was noted that phosphorylation of PKCδ, PICALM, and CDC37 were specifically enhanced in the tumor group, but few were identified in NT group." (PMID 36482371, 2022). "CDC37 is overexpressed in tumor cells, compared to normal cells, and CDC37/HSP90 synergistically facilitates the maturation of oncogenesis." (PMID 35453304, 2022). "In many tumor cells, Cdc37 overexpression is oncogenic, as it mediates the recruitment of kinases to the Hsp90 system and maintains their enzyme activity." (PMID 33663544, 2021). "For instance, the expression of Hsp90 or Cdc37 was used to identify potentially-responsive tumor types." (PMID 33672199, 2021). "The co-chaperone protein CDC37 (Cell division cycle 37) is well known to regulate multiple protein kinases and involved in tumor progression." (PMID 33976724, 2021). "Our study demonstrated that HSP90 and CDC37 are essential for a key component of the network, stressome release which permits the exit of HSPs and promotes tumor progression in CRPC." (PMID 32204513, 2020). "Our data indicate that modification of the carboxylic acid group of celastrol retained HSP90/CDC37 antagonist activity, as well as anti-tumor activity in HCC cell lines." (PMID 25051375, 2014). "Tumors from three HCC patients (HCC-1, HCC-2, and HCC-3) were confirmed to express high levels of CDC37 compared to their matched non-tumor liver tissues." (PMID 25051375, 2014). "We therefore evaluated the recently identified HSP90/CDC37 antagonist, celastrol, for its anti-tumor activity in HCC cell lines and patient-derived xenografts." (PMID 25051375, 2014). "CDC37 expression in these xenografts were maintained (compared to original HCC tumor levels), and expression levels were unaffected by treatment with all four compounds." (PMID 25051375, 2014). "Hsp90 and Cdc37 are both required for activity and stability of many tumor-inducing signaling protein kinases, and tumors appear to become addicted to these chaperones." (PMID 22624053, 2012). "We showed that compound 1 decreases Cdc37 phosphorylation on Ser13 both in U373 cells and in tumor-bearing mice." (PMID 22184283, 2011). "We show that Cdc37 and PP5/Ppt1 associate in Hsp90 complexes in yeast and in human tumor cells, and that PP5/Ppt1 regulates phosphorylation of Ser13-Cdc37 in vivo, directly affecting activation of protein kinase clients by Hsp90-Cdc37." (PMID 18922470, 2008).
tumor (continued). "Mechanistically, tumor cytosolic CDC37, shuttled via extracellular vesicles (EVs) into the endosomes of intratumor dendritic cells (DCs), inhibits antigen cross-presentation by locking antigen binding to HSP90 and precluding their translocation from endosomes to cytoplasm." (PMID 41215476, 2025). "Therefore, tumor EV-shuttled CDC37 locks antigen/chaperone interaction and impairs antigen cross-presentation in DCs." (PMID 41215476, 2025). "Mechanistically, they found that HSP90-enriched oral metastatic TDEs induce tumor-associated macrophage (TAM) polarization in M2 macrophages, supporting cancer progression, with simultaneous CDC37/HSP90α/β depletion attenuating the metastatic TDEs-driven tumor-initiating activity in oral cancer." (PMID 35629423, 2022). "Consequently, tumor cells can be selectively targeted by inhibiting HSP90-CDC37 interaction or down-regulation of CDC37." (PMID 26397138, 2015). "Thus, in future preclinical or clinical studies of HSP90/CDC37 antagonists, it is recommended to screen tumor models or patients for the expression of CDC37 and its client protein kinases before considering treatment with these agents." (PMID 25051375, 2014). "Based on the established role of these client protein kinases in hepatocarcinogenesis, we hypothesized that the direct disruption of HSP90 interaction with CDC37 by the small molecule celastrol would achieve desirable anti-tumor effects." (PMID 25051375, 2014). "The results with CDC37 are particularly intriguing as it suggests that chaperoned kinases in a tumor cell may enrich for a set of kinases necessary for cell survival." (PMID 24189400, 2013). "Finally, we examined the effect of PP5 overexpression on Cdc37 phosphorylation in a human tumor cell line." (PMID 18922470, 2008). "Moreover, targeting CDC37 is promising to enhance anti-tumor immunity and reverse ICB resistance." (PMID 41215476, 2025). "Given the contributory roles of multiple protein kinases in hepatocarcinogenesis, we hypothesized that disrupting the HSP90 and CDC37 chaperone complex may achieve anti-tumor effects in HCC, by inducing degradation and inhibiting phosphorylation of their client proteins kinases." (PMID 25051375, 2014). "Additionally, Cdc37 may be an attractive target in tumor types such as androgen independent prostate cancers that currently lack highly effective therapies." (PMID 21342561, 2011). "The results of IHC demonstrated that the expression of CDC37, GLA, HIF-1α and VPS35 was upregulated in the tumor tissues compared with corresponding normal tissues." (PMID 38528532, 2024). "Apart from the PI3K/AKT pathway (CDC37, IL6R), Epidermal-Mesenchymal transition (IL6R, SHC2), tumour metastasis and T1/T2 activation are highlighted (DLL1, STAT4, IL6R)." (PMID 36834486, 2023). "IFN-γ increases CUL5 expression and diminishes both Cdc37 and Hsp90 from HER2 receptor, resulting in less surface HER2, further tumor senescence, and repressed tumor growth." (PMID 37174034, 2023). "We have also examined the roles of the key co-chaperone CDC37 in the release of EV proteins including CD9 and epithelial-to-mesenchymal transition (EMT), a key event in tumor progression." (PMID 32204513, 2020). "CDC37, which is able to direct HSP90 proteins to the target protein and modulate their functions, was found to cooperate with c-Myc in tumor transformation in several tissue types." (PMID 31296583, 2019). "Second, increase in the interaction of HA with intracellular and surface receptors (CDC37, IHABP, RHAMM & CD44) activates the HA mediated signaling for the active invasive nature of the malignant tumor cells during early stage of tumor progression." (PMID 16401353, 2006). "RT‐PCR detection of budding RTP gene‐expressions in PDX model post two times 8 Gy irradiation revealed that most RTP gene levels (CST3, CDC37, IGFBP6, ISYNA1, RN7SL2) increased on day 9 when RTP cells were significantly enriched and partial fell back on day 82 when tumor repopulated." (PMID 36658726, 2023).
tumor (continued). "A single GIST biopsy sample P5 with undetectable expression of CK2 was deemed uninformative, due to lack of expression of KIT, p-KIT and CDC37, which suggest low tumour content." (PMID 31776458, 2020). "This may indicate that the role of CDC37 in BC is different, perhaps acting as a tumor suppressor gene rather than an oncogene." (PMID 39165691, 2024). "Therefore, the tumor cells, rather than normal cells, have increasing dependency on the Cdc37 level." (PMID 29699578, 2018).